COL6A1 (collagen type VI alpha 1 chain)
Diseases named in the same sentence as COL6A1 in open-access papers (continued):
Sharing a sentence is not in itself a finding about the gene and the disease.
muscular dystrophies (16 papers, 2012 to 2025). "Collagen VI–related disorders (COL6-RDs) are a group of rare muscular dystrophies caused by pathogenic variants in collagen VI genes (COL6A1, COL6A2, and COL6A3)." (PMID 40309777, 2025). "Here we aimed to model in the mouse a recurrent, deep-intronic, splice-activating, COL6A1 variant, associated with a severe form of Collagen VI-related muscular dystrophies (COL6-RDs), for the purpose of testing human-ready antisense therapeutics in vivo." (PMID 38585878, 2024). "Of note, the proteins encoded by genes linked to other muscular dystrophies such as COL6A1, CAV3, DYSF, DMD, TTN, and VCP and the strongest family sequencing candidates INTS1 and ANK2 were all found in nuclear envelope proteomics datasets." (PMID 31862442, 2020). "Mutations in COL6A1 are most famously linked to a wide range of muscular dystrophies of varying severity in humans." (PMID 33382735, 2020). "On the other hand, the genetic evidence provides statistical support for the causality of the COL6A1:c.289G>T for the observed muscular dystrophy." (PMID 26438297, 2015). "In conclusion, we provide the first comprehensive description of a clinically severe canine muscular dystrophy, most likely caused by a nonsense variant in the COL6A1 gene." (PMID 26438297, 2015). "We therefore conclude that the identified canine COL6A1 variant is most likely causative for the observed muscular dystrophy in Landseer dogs." (PMID 26438297, 2015). "Among other muscular dystrophies, 20 of 24 patients (83.3%) had variants in LAMA2 (n = 6), LMNA (n = 5), COL6A1 (n = 4), CHKB (n = 2), COL6A2 (n = 2), and COL6A3 (n = 1)." (PMID 40494860, 2025). "Multiple genes with high loading in LF1 relate to muscular dystrophy with the Dmd gene ranking in top 100 genes, and all 3 Col6a genes (Col6a1, Col6a2 and Col6a3 genes) responsible for Ulrich muscular dystrophy are present in the top 40 genes in LF1." (PMID 37000843, 2023). "Because gene mutations in COL6A1, COL6A2 and COL6A3 have been shown to result in muscular dystrophy, which indicated that collagen VI is particularly necessary for the vitality of skeletal muscle." (PMID 31286980, 2019). "We recently reported defective autophagy regulation in another animal model of muscular dystrophy, the collagen VI null (Col6a1–/–) mouse." (PMID 24292657, 2013). "In addition to the clinical similarities seen among these muscular dystrophies, both the Col6a1−/− and oim/oim mouse also exhibit mitochondrial dysfunction." (PMID 34066978, 2021). "However, mutations in COL6A1 and other COL6 chain genes also result in congenital muscular dystrophies and are similarly characterized by increased interstitial fibrosis and adipogenesis." (PMID 33317052, 2020). "Interestingly, fibroblasts cultured from one patient with a LAMA2-related muscular dystrophy exhibited reduced COLVI secretion, although no mutations were found in their COL6A1-3 genes, suggesting the important role of extracellular matrix homeostasis in skeletal muscle health." (PMID 34066978, 2021).
breast carcinoma (12 papers, 2008 to 2025). "Early studies using mice genetically ablated for COL6A1, which resulted in a functional deficiency in type VI collagen, showed that COL6A1 was critical for the growth of allografted breast cancer cells." (PMID 41228242, 2025). "Notably, COL5A1 and COL6A1, among the identified markers, have been linked to CAF and are closely associated with the progression, invasion, and metastasis of breast cancer." (PMID 40226936, 2025). "COL6A1 mediates Fzd7-Wnt5b to induce breast cancer mesenchymal-like stemness." (PMID 36167487, 2022). "Finally, two genes are associated with non-prostatic neoplasms: ELF3 with breast cancer and COL6A1 with astrocytoma." (PMID 20500816, 2010). "Second, the TCGA BRCA dataset (n = 821) with PAM50 subtypes called by RNAseq was used to validate the differentially expression of COL2A1, COL11A1, COL6A1, COL6A2, THBS1 and LUM among four breast cancer molecular subytpes in an independent cohort." (PMID 40927672, 2025). "In the HER2-negative breast cancer cohort treated with Bevacizumab, MMP2, COL5A2, COL6A1, DLK1, and MDK were identified as predictive of treatment response, aligning with their documented roles in angiogenesis and stromal interactions." (PMID 41139924, 2025). "Disease-specific survival discrepancy was observed comparing breast cancer patients of the upper and lower quartile of the collagen family (COL2A1, COL11A1, COL6A1, COL6A2), THBS1 and LUM gene expression signature (log-rank test, P = 0.06)." (PMID 40927672, 2025).
pancreatic cancer (12 papers, 2019 to 2025). "We found that Ccn1‐deficient pancreatic cancer cells exhibit reduced expression of collagens, including Col4a1, Col4a2, Col5a1, Col6a1, Col6a2, Col6a3, and Col8a1." (PMID 40287974, 2025). "Whittle and colleagues reported that Runx3 regulates a notable number of genes implicated in ECM functions, including Col6a1 and Spp1, to directly stimulate cell migration and dissemination and thereby promote metastasis in pancreatic cancer." (PMID 38240752, 2024). "Similarly, mRNA levels of Col5a1, Col6a1, Col6a2, Col6a3, and Col8a1 were significantly reduced in Ccn1‐deficient pancreatic tumors, while Col4a1 and Col4a2 were unaffected." (PMID 40287974, 2025). "Expression of COL6A1 is significantly elevated in different tumors such as lung, prostate, cervical, and pancreatic cancer compared to normal tissues." (PMID 37218885, 2023). "Previously, high expression of COL6A1 has been reported to predict poor prognosis in pancreatic cancer and cervical cancer, and similar effects of COL6A1/2/3 are also seen in triple-negative breast cancer (TNBC)." (PMID 36167487, 2022). "Recently, COL6A1 has been recognized as important for tumor growth and metastasis, and it has been reported to be expressed in a variety of cancers including cervical squamous cell carcinoma and pancreatic carcinoma." (PMID 40776410, 2025). "Previous studies demonstrated that COL6A1 expression is correlated to a metastatic behavior in pancreatic cancer and may also contribute to the process of brain metastasis in breast tumors." (PMID 37505240, 2023). "Furthermore, overexpression of COL6A1 enhances pancreatic cancer cell motility and metastasis, while COL6A1 knockdown leads to suppression of this metastatic ability." (PMID 33391546, 2021). "Metastatic nodules formed by pancreatic cancer cells lacking Col6a1 display stromal cell-derived collagen VI deposition, suggesting that collagen VI derived from either cancer cells or the stroma is an essential component of the metastatic niche." (PMID 36546396, 2022).
cervical cancer (11 papers, 2019 to 2025). A primary or metastatic malignant neoplasm involving the cervix. "There are a few studies regarding the expression and role of COL6A1 in human malignancies, although high expression of COL6A1 observed in prostate cancer, renal cell carcinoma, and cervical cancer was associated with poor survival outcome 7-9." (PMID 33391546, 2021). "Furthermore, increased expression of COL6A1 has been linked to enhanced motility and metastasis in lung, pancreatic, and cervical cancer cells, whereas reducing COL6A1 expression has been associated with decreased metastatic capabilities." (PMID 40776410, 2025). "The upregulated COL6A1 expression in the tissues of cervical cancer was related to poor clinical prognosis and treated as an important biomarker of cervical cancer progression." (PMID 34149809, 2021). "Cervical cancer has been seen initiated and progressed by an oncogene COL6A1." (PMID 35057823, 2022). "Recent evidence has proclaimed that COL6A1 was widely distributed in human malignant tumors, like prostate cancer, renal cell carcinoma, and cervical cancer, and involved in various biological functions of cancer cells, including cell migration, differentiation, and invasion." (PMID 35494018, 2022). "Our data revealed a close positive correlation between the expression of P4HA2 and collagen biosynthesis-related genes (Col4A1, Col5A1 and Col6A1) in cervical cancer, which is also consistent with a previous report of a positive correlation between collagen biosynthesis and P4HA2 in breast cancer." (PMID 32226497, 2020).
bladder cancer (9 papers, 2020 to 2024). "The functional experiments successfully verified that COL6A1 promoted the migration of bladder cancer cells as a risk factor, and bladder cancer cells were down-regulated after knocking down the expression of COL6A1." (PMID 36357874, 2022). "Survival analysis of bladder cancer patients revealed elevated expression COL6A1 and FBN1 is associated with a worse overall survival and progression of disease." (PMID 32922663, 2020). "In conclusion, COL6A1 is closely related to the malignant progression and prognosis of bladder cancer patients and the efficacy of immunotherapy, and it is a promising biomarker." (PMID 39559360, 2024). "Collagen alpha-1(VI) chain (COL6A1) was downregulated in the bladder cancer group in this biomarker discovery study." (PMID 37371512, 2023). "High expression of ECM-related gene COL6A1 predicts poor prognosis and poor immunotherapy response in bladder cancer." (PMID 37025405, 2023). "Meanwhile, the most interesting proteins downregulated in the samples of bladder cancer patients were: collagen alpha-1 (VI) chain (COL6A1), fructose biphosphate aldolase B (ALDOB) and mannan-binding lectin serine protease (MASP2)." (PMID 37371512, 2023). "Additionally, COL6A1 has been shown to inhibit bladder cancer invasion by down-regulating the activities of matrix metalloproteinases 2 (MMP-2) and MMP-9." (PMID 38339238, 2024). "In addition, COL6A1 expression level was closely associated with immunotherapy in patients with advanced bladder cancer, and bladder cancer patients with high COL6A1 expression showed poorer responsiveness and efficacy to immunotherapy." (PMID 39559360, 2024). "More importantly, seldom studies have explored the relationship between COL6A1, LAMA2, and bladder cancer, thus of great significance in our study." (PMID 36357874, 2022). "After knocking down the expression of COL6A1 and LAMA2, the Transwell assay showed that the migration ability of bladder cancer cells was down-regulated." (PMID 36357874, 2022). "COL6A1 and LAMA2 were again validated to promote the migration of bladder cancer cells." (PMID 36357874, 2022).
congenital muscular dystrophy (9 papers, 2017 to 2025). A muscular dystrophy that is characterized by diminished muscle tone (hypotonia), progressive muscle weakness and degeneration (atrophy), abnormally fixed joints, spinal rigidity, and delays in reaching motor milestones such as sitting or standing unassisted. "Collagen VI-related dystrophies are a subtype of congenital muscular dystrophy caused by pathogenic variants in COL6A1, COL6A2 or COL6A3 genes affecting skeletal muscles and connective tissue." (PMID 33750322, 2021). "Mutations in the COL6A1, COL6A2 and COL6A3 genes result in congenital muscular dystrophy, arguing that collagen is critical for skeletal muscle development and function." (PMID 28755659, 2017). "In addition, mutations in COL6A1, COL6A2 and COL6A3 genes were considered causal mutations for congenital muscular dystrophy, a disease that affects connective and muscular tissue in humans." (PMID 32379844, 2020). "Causative variants in COL6A1, COL6A2 and COL6A3 genes result in skeletal muscle disorders, collectively called “collagen VI myopathies”, which represent a common type of congenital muscular dystrophy (CMD), identified in 20.24% of Italian CMD patients." (PMID 41154655, 2025).
glioma (9 papers, 2009 to 2024). A benign or malignant brain and spinal cord tumor that arises from glial cells (astrocytes, oligodendrocytes, ependymal cells). "Glioma‐related studies uncovered that COL6A1 was upregulated in tumor tissues and associated with poor prognosis." (PMID 38887185, 2024). "COL6A1 is highly expressed in glioma tissues and associated with clinical prognosis of GBM patients." (PMID 38887185, 2024). "Moreover, COL6A1 was found to be differentially expressed across glioma grades, with higher expression levels associated with more advanced tumor grades." (PMID 38887185, 2024). "Some researchers also reported that the over-expression of COL6A1 contributed to poor prognosis of renal clear cell carcinoma and glioma patients and enhanced probability of lung cancer cell metastasis." (PMID 36357874, 2022). "Recently, COL6A1 has been reported to influence clinical outcomes in patients with glioma, with increased expression levels, especially in GSCs." (PMID 35494018, 2022). "We screened this series of differentially expressed proteins, comprehensively analyzed the proteins whose molecular functions were related to angiogenesis and co-expressed with P4HA1 in glioma tissues, and finally identified COL6A1." (PMID 35494018, 2022). "COL6A1 was uncovered to express characteristically higher in glioma than in surrounding normal tissues and extensively exist in the perivascular region." (PMID 35494018, 2022). "Additionally, IHC results exhibited elevation of COL6A1 protein in high‐grade gliomas relative to normal brain tissue." (PMID 38887185, 2024). "This analysis showed that more than 70% of M6 genes were highly correlated with each other, either negatively or positively, in glioma tumors, confirming that at least a subset of the previously identified COL6A1-correlated genes displays a similar behavior also in tumor samples from patients." (PMID 37505240, 2023). "The study also has some limitations on whether P4HA1 and COL6A1 can promote angiogenesis in other type tumors like glioma remains to be defined." (PMID 35494018, 2022). "Thus, our findings of this study provide new clues for exploring the role of COL6A1 in glioma angiogenesis and progression." (PMID 35494018, 2022). "COL6A1 expression is generally limited to the perivascular region in glioblastomas but has also been observed in glioma cells that are organized in pseudopalisades, a familiar morphologic feature that links hypoxia, vascular pathology, and angiogenesis in glioblastoma." (PMID 35494018, 2022). "Pan-cancer examination revealed a correlation between COL6A1 and LAIR1 expression and across glioma lineages." (PMID 38357919, 2024). "Collagen type VI alpha 1 (COL6A1) was identified as hub gene via comprehensive bioinformatic analysis based on RNA sequencing (RNA‐seq) and public glioma datasets." (PMID 38887185, 2024). "Altering the expression of P4HA1 in GSCs altered the expression of COL6A1 and CD31, thereby inducing glioma angiogenesis." (PMID 35494018, 2022). "FN1, COL1A1, COL6A1, and LTBP1 were significantly expressed in GBM compared with WHO grade II and III glioma." (PMID 34638384, 2021). "Of note, genes displaying a strong negative correlation (r < − 0.4; n = 5) with COL6A1 were particularly expressed in both normal brain samples and low-grade gliomas relative to higher grade tumors." (PMID 37505240, 2023). "Although COL6A1 has been studied to promote tumor progression and metastasis in other types of tumors, its specific function of COL6A1 has never been clarified in glioma." (PMID 35494018, 2022).
liver fibrosis (9 papers, 2014 to 2025). "Over time, at 40w and 80w, the elevated expression of Col6a1 and Col6a2 could be associated with liver fibrosis and extracellular matrix regulation." (PMID 40537154, 2025). "Importantly, PI3K-AKT and focal adhesion-related proteins, such as PDGFRβ, PIKR3R1, ITGB5, COL1A1, COL6A1, COL6A3, and LAMA5, are mainly associated with liver fibrosis." (PMID 38469403, 2024). "Increased COL6A1 tissue levels are present in lung fibrosis, liver fibrosis and keloid scarring." (PMID 33658982, 2020). "The antifibrotic properties of CA were further supported by identifying many liver fibrosis-specific seed genes in PPI analysis, including TIMP2, COL6A1, and COL6A2." (PMID 37175790, 2023). "Therefore, our study investigated the role of COL6A1, COL6A2, COL6A3, and COL1A1 expressions on liver fibrosis in BA patients in Indonesia." (PMID 38041174, 2023). "Collagen VI (COL6A1, COL6A2, and COL6A3) genes, but not COL1A1, have been associated with liver fibrosis." (PMID 38041174, 2023).
lung carcinoma (9 papers, 2014 to 2023). "For example, the ligand COL6A1, which is predominantly upregulated in epithelial cells (malignant cells), has been reported to promote bone metastasis in lung cancer." (PMID 37880703, 2023). "COL6A1 is highly expressed in non-small cell lung cancer tissue samples with bone metastases, and overexpressed COL6A1 in lung cancer cells increases the adhesion of these cells to osteoblasts." (PMID 36167487, 2022). "A report by Chiu indicated that COL6A1 knockdown suppresses the metastatic ability of lung cancer cells, whereas overexpression of COL6A1 has the opposite effect." (PMID 26317545, 2015). "Also, COL6A1 plays a role as an oncogene in breast and lung cancer where it regulates anti-apoptosis, proliferation, angiogenesis, and metastasis." (PMID 37218885, 2023). "COL6A1 is reportedly a crucial regulator of lung cancer invasion and metastasis." (PMID 34838074, 2021). "Besides, the up-regulation of COL6A1 expression induces tumorigenesis in prostate cancer cells in vivo has also been reported in a study about castration-resistant prostate cancer and enhanced probability of lung cancer cell metastasis in another research." (PMID 36357874, 2022).
Obesity (8 papers, 2019 to 2026). Accumulation of substantial excess body fat. "We also analyzed the expression of collagen type 6a1 (Col6a1), which is enriched in adipocyte extracellular matrix and contributes to obesity-related inflammation of adipose tissue." (PMID 34502211, 2021). "Obesity robustly induced transcription of fibrotic genes in both subcutaneous white AT (scWAT) and visceral white AT (vWAT), including Col1a1, Col6a1, and Mmp2, consistent with RNAseq analysis of adipocytes that acquire a fibroblast-like transcriptional signature in response to a HFD feeding." (PMID 36229481, 2022). "Interestingly, ASPC3 was uniquely enriched for COL1A1, COL6A1, FN1, LOX, and LUM, which are fibrosis markers recently associated with a specific subset of PDGFRA+ progenitor cells in murine model of obesity." (PMID 36313560, 2022). "Interestingly, some scientists believe that obesity is an inflammatory condition that is associated with increased extracellular matrix (ECM) gene expression, whereas the collagen 6A1(COL6A1) gene is the primary gene in the ECM." (PMID 34571718, 2021). "Stromal fibroblasts from mice with obesity contribute to basement membrane expansion and abundant ECM deposition, increasing SPARC, ELN, COL3A1, and COL6A1 gene expression." (PMID 40847127, 2025). "RNA-sequencing of human subcutaneous white adipose tissue revealed that obesity increases expression of collagen genes COL4A2, COL5A1, COL5A2, COL6A1, COL12A1, and COL16A1." (PMID 40847127, 2025).